SPDYE11 (speedy/RINGO cell cycle regulator family member E11)
Description:
Acts as a modulator of the nicotinic acetylcholine receptor alpha-7 (CHRNA7) activity.
Tractability: No criterion of Open Targets' tractability assessment is met for any kind of drug.
Gene: Protein-coding gene on chromosome 7 (73,047,862 to 73,057,911, reverse strand). Ensembl gene ENSG00000275976.
Gene Ontology:
Molecular function: acetylcholine receptor regulator activity; protein kinase binding
Homologues: Orthologues: rat Spdye4 (49% identical), mouse Spdye4a (48% identical), mouse Spdye4b (44% identical). Paralogues in human: SPDYE10 (100% identical), SPDYE17 (100% identical), SPDYE8 (100% identical), SPDYE9 (100% identical), SPDYE13 (99% identical), SPDYE14 (99% identical), SPDYE15 (99% identical), SPDYE12 (99% identical), SPDYE3 (89% identical), SPDYE18 (83% identical), SPDYE16 (83% identical), SPDYE2 (83% identical), and 6 more.